AR (androgen receptor)
Diseases named in the same sentence as AR in open-access papers (continued):
Sharing a sentence is not in itself a finding about the gene and the disease.
triple-negative breast carcinoma (continued). "Thus, loss of SNAI1 in the context of triple-negative breast carcinoma cells promotes an intermediary luminal progenitor phenotype that gains differentiation plasticity based on the dual transcriptional action of FOXA1 and AR." (PMID 36171192, 2022). "It has been reported that AR expression was negative in triple-negative breast carcinoma, and it was suggested that the loss of AR may be correlated with poor prognosis." (PMID 34226586, 2021). "Interestingly, triple-negative breast cancers of women often express AR and might respond to ADT or AR blockade." (PMID 34768683, 2021). "Similarly, AR is expressed in a significant number of triple-negative breast cancers." (PMID 32374753, 2020). "In multivariable analysis, androgen receptor expression was most significantly associated with worse local recurrence-free survival after radiation therapy (hazard ratio of 3.58) suggesting that androgen receptor expression may be a biomarker of radiation response in triple-negative breast cancer." (PMID 28840192, 2017). "Androgen receptor is expressed in approximately 70 to 90% of invasive breast carcinomas, which has prognostic relevance in basal-like cancers and in triple-negative breast cancers, suggesting that it could have a biological relevance in the course of the disease." (PMID 27746764, 2016). "Interestingly, HER2 expression seems to interact with AR in HR negative tumors in prognostic terms, as in our previous study in the same cohort, AR positivity was a positive prognostic factor only in the molecular subgroup of triple negative breast cancer (as defined by ER/PR/HER2 negativity)." (PMID 25070172, 2014). "Interestingly, studies suggest that older women with triple-negative breast cancer exhibit a higher frequency of luminal androgen receptor and mesenchymal-like subtypes, which could partly explain the observed differences in tumor aggressiveness compared with younger patients." (PMID 40373794, 2025). "In triple-negative breast cancers (TNBC), AR expression is correlated with a lower Ki67 labeling index, lower stage, lower histological grade, and favorable outcomes." (PMID 39497884, 2024). "Although the basal subtype transcends the group and contributes approximately 80% to triple-negative breast cancer (TNBC) cases, the exceptionally appearing mesenchymal and luminal androgen receptor (LAR) subtypes portray an unfathomable clinical course." (PMID 36612226, 2022). "Here, we assessed the effect of hypoxia (1% Oxygen) on the tumor suppressor Annexin A6 (AnxA6) and the response of triple-negative breast cancer (TNBC) cells to epidermal growth factor receptor (EGFR) and androgen receptor (AR) targeted therapies." (PMID 36230969, 2022). "However, multivariate analysis showed that only higher AR expression could be considered as an independent prognostic biomarker for poorer overall survival in triple-negative breast cancer patients (TNBC) (HR 10.9, 95% CI 1.43–83.67; p = 0.021), what could be Croatian population-related." (PMID 36294994, 2022). "Within the ER−PR-negative (PR–) subset, 34% (15/44) of HER2– tumors (triple-negative breast cancer, TNBC) were AR+, and among HER2-positive tumors, 86% (12/14) were AR+." (PMID 28643022, 2017). "Therefore AR targeting in the clinical settings may be affected by this process and combined targeting of AR and GR might be the ideal therapy for the AR positive, triple negative breast cancer." (PMID 25781993, 2015). "provided an in-depth analysis of 465 cases of triple-negative breast cancer (TNBC) by genomic and transcriptomic sequencing, and classified TNBC into four subtypes: luminal androgen receptor (LAR), immunomodulatory (IM), basal-like immune- suppressed (BLIS) and mesenchymal-like (MES)." (PMID 40881682, 2025).
triple-negative breast carcinoma (continued). "Although defined by the absence of estrogen receptor, progesterone receptor, and ERBB2 expression, genomic analyses have revealed intrinsic triple-negative breast cancer subtypes, including basal-like (BL1 and BL2), mesenchymal, luminal androgen receptor, and immunomodulatory subtypes." (PMID 40373794, 2025). "Androgen receptor (AR)-negative triple-negative breast cancer (TNBC), often termed quadruple-negative breast cancer (QNBC), disproportionately impacts women of African descent, leading to poorer overall survival (OS)." (PMID 39769441, 2024). "There are currently no approved targeted treatments for quadruple-negative breast cancer [QNBC; ER−/PR−/HER2−/androgen receptor (AR)−], a subtype of triple-negative breast cancer (TNBC)." (PMID 39335162, 2024). "In triple negative breast cancer (TNBC), the luminal androgen receptor (LAR) subtype, characterized by the expression of androgen receptor, is associated with better prognosis, less chemotherapy responsiveness, and lower pathologic complete response after neoadjuvant treatment." (PMID 37085500, 2023). "In addition, RORγ activates cholesterol biosynthesis in triple-negative breast cancer (TNBC) and stimulates androgen receptor (AR) transcription in castration-resistant prostate cancer (CRPC)." (PMID 36316442, 2022). "Accordingly, there has been increasing support for classification of androgen receptor-negative triple-negative breast cancer or quadruple-negative breast cancer (QNBC)." (PMID 35203574, 2022). "Many triple-negative breast cancers, characterized by the absence of ERα, progesterone receptor (PR) and human epidermal growth factor receptor 2 (Her2), also possess ERβ and an androgen receptor (AR)." (PMID 32354130, 2020). "Triple-negative breast cancer (TNBC) has been subdivided into six distinct subgroups: basal-like 1 (BL1), basal-like 2 (BL2), mesenchymal (M), mesenchymal stem–like (MSL), immunomodulatory (IM), and luminal androgen receptor (LAR)." (PMID 31836816, 2019). "The percentage of mature stroma was significantly higher in basal like, AR positive-ER/PR negative, and AR positive-triple negative breast cancer." (PMID 31584964, 2019). "Apocrine tumors (ER negative, AR positive) with HER2 positivity associated with poorer survival, while AR did not appear to impact OS in triple negative breast cancer (TNBC) cases." (PMID 28085048, 2017). "Consistently, in a clinical study of non-metastatic triple-negative breast cancers, co-expression of AR with FoxA1 defines a sub-group of patients with a distinct behavior reminiscent of luminal cancers." (PMID 26797644, 2016). "In our previous report, we suggested that DAX-1 might be a more effective target than AR in triple-negative breast cancer because the overall expression rate of DAX-1 is high, even in these triple-negative breast cancers." (PMID 22035181, 2011). "However, AR expression in estrogen receptor-negative (ER-negative) subtypes, including triple-negative breast cancer (TNBC), is less clearly understood, and its role in promoting tumorigenesis and metastasis in these cases remains controversial." (PMID 40286049, 2025). "PSMA expression in NPCaT may aid prognostication, for example, PSMA expression in non-metastatic triple negative breast cancer confers worse prognosis with higher relapse and reduced response to androgen receptor inhibition." (PMID 35254481, 2022). "However, the efficacy of HC-1119 in inhibition of AR function in triple-negative breast cancer (TNBC) has not been studied." (PMID 35960413, 2022). "This pathway has been also involved in androgen induced migration of triple negative breast cancer cells but not in PC cells, where the Fak phosphorylation, the activation of cell motility and invasion appear to be strictly dependent on the formation of the AR/FlnA complex." (PMID 35011576, 2021).
triple-negative breast carcinoma (continued). "There is growing evidence that the response to chemotherapy may be affected by Androgen Receptor (AR) expression suggesting that triple-negative breast cancers (TNBC) AR+ and quadruple negative breast cancer (QNBC) subtypes may have different diseases behavior." (PMID 32102539, 2020). "In a low percentage of triple-negative breast cancers, PI3K/AKT/mTOR pathway is activated, which lead to the hypothesis that inhibition of the PI3K signaling pathway may ensure a proper treatment for patients diagnosed with mesenchymal and luminal androgen receptor (LAR) types of TNBCs." (PMID 28445140, 2017). "Based on the androgen receptor (AR) expression, triple-negative breast cancer (TNBC) can be subdivided into AR-positive TNBC and AR-negative TNBC, also known as quadruple-negative breast cancer (QNBC)." (PMID 33213491, 2020). "AR and FOXA1 expression were evaluated by immunohistochemistry in 333 non-metastatic triple-negative breast cancers (TNBC)." (PMID 29880907, 2018). "Drug name (Alternative name): Enobosarm (GTx-024)Type of drug: Small MoleculeMechanism(s) of Action: Non-steroidal selective androgen receptor modulator (SARM)Generally used for: Treatment of Stress Urinary Incontinence and Triple Negative Breast Cancer." (PMID 29254284, 2017). "In subgroup analysis, AR could predict DFS outcome in estrogen receptor (ER) positive (HR 0.45, 95% CI 0.34-0.59), ER negative (HR 0.42, 95% CI 0.26-0.67), and triple negative breast cancer (HR 0.40, 95% CI 0.23-0.69)." (PMID 24324816, 2013). "A meta-analysis of public gene expression databases indicated that ACSL4 expression is positively correlated with a unique subtype of triple negative breast cancer (TNBC), characterized by the absence of androgen receptor (AR) and therefore referred to as quadruple negative breast cancer (QNBC)." (PMID 24155918, 2013). "The exact effect of AR expression on TNAC has not been elucidated, together with the question of whether anti-AR therapy can be applied in TNAC patients, whereas in triple-negative breast cancers (TNBC) of nonapocrine subtype, the expression of AR and its consequent effects are well documented." (PMID 35329934, 2022).
metastatic prostate carcinoma (210 papers, 2006 to 2026). A carcinoma that arises from the prostate gland and has spread to other anatomic sites. "To investigate the role of Abl kinases in tumor progression, we used RNAi to generate Abl-deficient cells in a model of androgen receptor-indifferent, metastatic prostate cancer." (PMID 37746268, 2023). "AR copy number amplifications or gain of function mutations in the ligand binding domain commonly found in metastatic prostate cancer (~50%) were identified in our cohort." (PMID 35269713, 2022). "Alterations of AR are indeed rare in treatment-naïve metastatic prostate cancer, probably being random “passenger” mutations." (PMID 34638258, 2021). "Various AR mutations have been observed in clinical samples from metastatic prostate cancer patients." (PMID 30271980, 2018). "In metastatic prostate cancer, the presence of the androgen receptor (AR) splice variant V7 in CTCs was previously demonstrated to be strongly associated with resistance to endocrine agents, but not to chemotherapy." (PMID 29063679, 2018). "The ability to rapidly determine how a mutation affects ligand responses is critical because it is known that the frequency of AR mutations increases in metastatic prostate cancer." (PMID 18978937, 2008). "Apalutamide is a selective androgen receptor inhibitor indicated for the treatment of hormone-sensitive and metastatic prostate cancer associated with castration or treatment to inhibit androgen secretion, or resistant to chemical castration with a high risk of metastatic progression." (PMID 40905521, 2025). "Calcium influx was found to increase cell migration in AR-deficient metastatic cell lines DU145 and PC-3 calpain cleavage of filamin A in AR-deficient metastatic prostate cancer cell lines.This is most likely due to the cellular redistribution of calpain, induced by calcium (Ca2+)." (PMID 38958472, 2024). "The implication that THCs are linked to metastatic prostate cancer led us to examine whether AR signaling is deregulated in these cells." (PMID 37848444, 2023). "Another study has shown that resistance to hormonal therapy in metastatic prostate cancer patients may be predicted by detecting androgen receptor splice variant 7 (AR-V7) in plasma-derived exosomal RNA." (PMID 33407894, 2021). "Enzalutamide (ENZ), a next-generation androgen receptor (AR) inhibitor, is a cornerstone treatment for metastatic prostate cancer." (PMID 41608626, 2026). "Longitudinal biopsy analysis in metastatic prostate cancer showed that AR inhibition enhanced immune cell and IFNγ signatures." (PMID 41486951, 2026). "Treatment of locally advanced and metastatic prostate cancer (PC) with androgen receptor-targeting (AR-targeting) therapies has limited durability, with disease eventually progressing to castrate-resistant PC (CRPC)." (PMID 41919500, 2026). "This study represents the first layer-by-layer analysis of macular thickness in patients with metastatic prostate cancer treated with androgen receptor pathway inhibitors compared with age-matched healthy controls." (PMID 40647681, 2025). "Androgen deprivation therapy (ADT) and next-generation androgen receptor pathway inhibitors (ARPI) are increasingly combined with PARP inhibitors (PARPi) in metastatic prostate cancer (mPCa)." (PMID 41488638, 2025). "Enzalutamide and abiraterone acetate are the first agents of the second generation of androgen receptor pathway inhibitors (ARPI) for metastatic prostate cancer (mPC)." (PMID 41436774, 2025). "The objective of this review is to summarize the roles of RSGs in metastatic prostate cancer (mPCa) and their interaction with the androgen receptor (AR), which regulates this disease." (PMID 41301045, 2025). "Bicalutamide, a first-generation androgen receptor (AR) inhibitor approved in the United States in 1995, has been commonly used for metastatic prostate cancer." (PMID 40496458, 2025).
metastatic prostate carcinoma (continued). "Androgen receptor pathway inhibitors (ARPI) are commonly used in addition to androgen deprivation therapy (ADT) for metastatic prostate cancer (mPC)." (PMID 41436774, 2025). "The androgen receptor inhibitor enzalutamide is one of the principal treatments for metastatic prostate cancer." (PMID 40624104, 2025). "Management of metastatic prostate cancer often requires combining androgen deprivation therapy (ADT) with novel androgen receptor signaling inhibitors (ARSIs)." (PMID 41176642, 2025). "Standard-of-care treatments for patients with metastatic prostate cancer aim to block the activation and/or signaling of the androgen receptor (AR)." (PMID 39858071, 2025). "Androgen-receptor pathway inhibitors (ARPIs) have dramatically changed the management of advanced/metastatic prostate cancer (PCa)." (PMID 39237679, 2025). "It is followed by Bavdegalutamide, which aims to degrade the androgen receptor in metastatic prostate cancer, and NX-5948, which targets BTK, a key driver in chronic lymphocytic leukemia." (PMID 41515330, 2025). "Currently, ARV-110, the first PROTAC designed to degrade the androgen receptor, is in clinical trials for metastatic prostate cancer." (PMID 41193953, 2025). "Novel hormone therapies (NHT) targeting the androgen receptor (AR) pathway have become the standard of care for metastatic prostate cancer." (PMID 41079787, 2025). "Androgen receptor signaling inhibitors (ARSIs) have demonstrated a survival benefit in metastatic prostate cancer." (PMID 40536697, 2025). "Androgen deprivation therapy (ADT), androgen receptor (AR) pathway inhibitors (ARPi), and chemotherapy are standard treatments for locally advanced or metastatic prostate cancer." (PMID 40627156, 2025). "Current intensive therapies for metastatic prostate cancer include radiation, docetaxel, and novel androgen receptor signaling inhibitors, such as abiraterone, darolutamide, enzalutamide, and apalutamide, in addition to ADT." (PMID 39516672, 2024). "Abiraterone (Abi) is an androgen receptor signaling inhibitor that significantly improves patients’ life expectancy in metastatic prostate cancer (PCa)." (PMID 37634036, 2024). "The landscape of treating metastatic prostate cancer has evolved with the addition of Androgen Receptor pathway inhibitor (ARPI) to Androgen Deprivation Therapy (ADT), significantly improving survival rates." (PMID 38779087, 2024). "Several treatment strategies use upfront chemotherapy or androgen receptor axis‐targeting therapies for metastatic prostate cancer." (PMID 36806727, 2023). "Although the second-generation androgen receptor inhibitors and taxanes have recently been recommended for the initial treatment of metastatic prostate cancer, bicalutamide and flutamide are still used in a large number of cases." (PMID 37118708, 2023). "Although androgen receptor (AR) amplification is a relatively common genetic alteration in metastatic prostate cancer, some reports indicate that the alterations are less frequent in ductal adenocarcinomas." (PMID 36573306, 2023). "This evidence suggests that GLDC is highly expressed in metastatic prostate cancer and has a regulatory relationship with AR and AR-V7." (PMID 37781511, 2023). "Metastatic prostate cancer can originate from hormone-sensitive disease (mHSPC) whose growth is mediated through activation of the androgen receptor." (PMID 36980735, 2023). "Currently, the standard of care for metastatic prostate cancer is medical castration in conjunction with chemotherapeutic agents and newer anti-androgen/androgen receptor therapies." (PMID 38239314, 2023).